CD47 (CD47 molecule)
Diseases named in the same sentence as CD47 in open-access papers (continued):
Sharing a sentence is not in itself a finding about the gene and the disease.
breast tumors (continued). "Breast tumor patients with high expression of CD47 showed poor survival and prognosis; cGAMP and anti-CD47 combination therapy effectively suppressed tumor growth, whereas monotherapy with anti-CD47 did not inhibit tumors." (PMID 35265630, 2021).
small cell lung carcinoma (19 papers, 2019 to 2025). Small cell lung cancer (SCLC) is a highly aggressive malignant neoplasm, accounting for 10-15% of lung cancer cases, characterized byrapid growth, and early metastasis. "Recent research has indicated that CD47 blockade can activate macrophages and achieve a T-cell-independent abscopal effect in small-cell lung cancer." (PMID 38169608, 2024). "Some cancerous cells, e.g., in small cell lung cancer, overexpress CD47 and therefore avoid phagoptosis." (PMID 34685548, 2021). "A study of small-cell lung cancer demonstrated that CD47-blocking antibody or inactivation of the CD47 gene suppressed the growth of tumors with high expression of CD47." (PMID 31781673, 2019). "Pharmacological inhibition of the immune-checkpoint molecule CD47 has shown promising results in preclinical small-cell lung cancer (SCLC) models, whereas anti-programmed death-ligand 1 (PD-L1) inhibitors have been recently implemented in the standard of care of advanced-stage SCLC patients." (PMID 36399951, 2022). "Moreover, combined therapies, including the usage of the CD47 antagonist CV1 with lorvotuzumab (anti-CD56 antibody) can significantly enhance the phagoptosis of cancer cells in small-cell lung cancer." (PMID 34685548, 2021). "CD47 antibody Hu5F9-G4 showed enhancement of phagocytic potential of macrophages and suppression of tumor cells in small cell lung carcinoma (SCLC)." (PMID 39003350, 2024). "The clinical trial involving the small molecule inhibitor RRX-001 on small cell lung cancer (SCLC) exhibited a reduction in SIRPα expression on macrophages and CD47 expression, resulting in potent antitumor activity and hypotoxicity." (PMID 37892995, 2023). "CD47 blockade combined with radiotherapy promotes abscopal effects to inhibit distant, non-irradiated small cell lung cancer." (PMID 40835598, 2025).
lung adenocarcinoma (18 papers, 2019 to 2026). A carcinoma that arises from the lung and is characterized by the presence of malignant glandular epithelial cells. "KRAS mutation status is positively correlated with CD47 expression in several lung adenocarcinoma cohorts." (PMID 36413402, 2023). "In this study, we established a positive correlation between KRAS mutation status and CD47 overexpression in patients with lung adenocarcinoma." (PMID 36413402, 2023). "To further explore the clinical relevance of our findings, we assessed the correlation of KRAS mutation status with CD47 expression in 3 independent lung adenocarcinoma cohorts." (PMID 36413402, 2023). "Moreover, the protein level of RAGA is negatively correlated with CD47 and associated with longer survival in clinical lung adenocarcinoma patients." (PMID 36823443, 2023). "To validate the clinical relevance of our findings, we assessed the correlation between RASON and CD47 expression in two independent lung adenocarcinoma cohorts." (PMID 40128846, 2025). "This suggests that in the future, we can combine IGSF10 restoration strategies with CD47/CD276 blockade to inhibit the progression of lung adenocarcinoma." (PMID 41447338, 2025). "This was consistent with IFT57 being the top-ranked gene for coexpression with CD47 in lung adenocarcinoma and a previous analysis of TCGA data." (PMID 39201643, 2024). "In summary, these results from 3 independent lung adenocarcinoma cohorts were consistent with each other and confirmed that KRAS mutation status is positively correlated with CD47 expression in patients with lung adenocarcinoma." (PMID 36413402, 2023). "In this study, we reveal RAGA as a negative regulator of CD47 stability thus involved in the regulation of phagocytosis and lung adenocarcinoma progression." (PMID 36823443, 2023). "Our study thereby not only reveals a mechanism by which RAGA regulates CD47 lysosome degradation, but also suggests RAGA is a potential diagnostic biomarker of lung adenocarcinoma." (PMID 36823443, 2023). "We first analyzed CD47 expression on the surface of tumor cells isolated from the 18 paired lung adenocarcinoma patient samples by flow cytometry." (PMID 36413402, 2023). "We, therefore, performed a clinical analysis of RAGA and CD47 protein expression in a commercial tissue chip of lung adenocarcinoma patient samples with an immunohistochemistry approach." (PMID 36823443, 2023). "Clinical analysis shows that RAGA and CD47 proteins are negatively correlated in lung adenocarcinoma patient samples." (PMID 36823443, 2023). "We stained CD47 in a clinical lung adenocarcinoma tissue sample with an immunohistochemistry approach." (PMID 36823443, 2023). "RAGA plays a tumor suppressor role in lung adenocarcinoma by promoting the lysosome degradation of CD47." (PMID 36823443, 2023). "In the third cohort, we determined the KRAS mutation status and the expression levels of CD47, p-STAT3, and miR-34a in 100 pairs of lung adenocarcinoma and normal tissue samples." (PMID 36413402, 2023). "Our study collectively demonstrates that CD47 undergoes lysosome-dependent degradation in lung adenocarcinoma." (PMID 36823443, 2023). "To determine the clinical relevance of the RAGA/CD47 axis in human patients, we first performed the analysis of the GEO lung adenocarcinoma database on the kmplot.com website." (PMID 36823443, 2023). "SPC-A-1 is a human lung adenocarcinoma cell with moderate expression of CD47 glycoprotein; thus, we increased our dose-response concentrations to a maximum of 200 nM." (PMID 35646646, 2022). "We found that expression of CD47 and MHC class I could vary in lung adenocarcinoma specimens depending on their driver mutation." (PMID 38483480, 2024). "The clinical analysis not only supports the mechanistic role of RAGA in promoting CD47 degradation, but also reveals that RAGA alone and in combination with CD47 might be potential molecular markers in lung adenocarcinoma diagnosis." (PMID 36823443, 2023).
lung adenocarcinoma (continued). "Retrospective analysis of a published dataset of microarray expression data from frozen primary lung adenocarcinoma specimens allowed us to investigate CD47 and CRT mRNA levels in patients (N = 226) with different oncogenic driver mutations (GEO accession number GSE31210)." (PMID 32082304, 2019). "Thus, patients with KRAS-mutant lung adenocarcinoma might be especially sensitive to anti-CD47 immunotherapy." (PMID 36413402, 2023). "It has been recently reported in lung adenocarcinoma patients and a tumor cell injection model that activated KRAS signaling triggers CD47 expression on tumor cells inhibiting their phagocytotic elimination." (PMID 40360735, 2025). "Both CD47 and MHC class I molecules were also highly expressed across lung adenocarcinoma specimens in the TCGA database." (PMID 38483480, 2024). "In this study, we demonstrate that CD47 can be degraded through the endocytosis/lysosome pathway and the degradation is promoted by the RAGA protein in lung adenocarcinoma." (PMID 36823443, 2023). "CD47 and p-STAT3 protein levels were consistently upregulated, and miR-34a was downregulated in the lung adenocarcinoma samples compared with the paired normal controls, regardless of KRAS mutation status." (PMID 36413402, 2023). "The mRNA expression of CD24, CD47 and CD155 was further verified in colon adenocarcinoma (COAD), liver hepatocellular carcinoma (LIHC), lung adenocarcinoma (LUAD) and stomach adenocarcinoma (STAD) patient samples via cDNA microarray." (PMID 38016957, 2023). "In the second cohort, we performed IHC analysis of CD47 and RASON expression on an in-house-generated tissue microarray containing paired tumor and adjacent normal tissue samples from nine patients with KRAS-mutant lung adenocarcinoma." (PMID 40128846, 2025). "Neither CD47 nor IFT57 mRNA expression was significantly correlated with overall survival in lung adenocarcinoma using a median cutoff." (PMID 39201643, 2024). "Moreover, while high p-AKT expression was positively correlated with poor overall survival in patients with lung adenocarcinoma, coordinated activation of KRAS (p-AKThi) and CD47 further increased the probability of a poor prognosis (HR, 1.81 vs. 1.46)." (PMID 36413402, 2023). "The strong positive Spearman's correlation for lung squamous carcinoma contrasted with a lack of correlation for lung adenocarcinoma (r = −0.01, p = 0.89), further suggesting that the relationship between CD47 and SLFN11 expression is cancer type specific." (PMID 31632920, 2019). "Our analysis of large transcriptomic dataset identified higher expression levels of CD47 mRNA, but not of CRT mRNA, in primary lung adenocarcinomas with EGFR mutations as compared to those with different oncogenic mutations." (PMID 32082304, 2019). "In the second cohort, we performed IHC analysis of CD47 and p-STAT3 expression in an in-house–generated tissue microarray containing paired tumor samples and adjacent normal tissue samples from 12 patients with KRASMUT lung adenocarcinoma and 28 patients with KRASWT lung adenocarcinoma." (PMID 36413402, 2023). "We firstly performed flow cytometry to detect the expression levels of PD‐L1 and CD47 on triple‐negative breast cancer (TNBC) cells MDA‐MB‐231 and 100 ng/mL IFN‐γ pre‐treated lung adenocarcinoma cells A549." (PMID 37974395, 2023). "Results of these analyses indicated that CD47 was overexpressed in tumors compared to adjacent non-tumor oral tissues and was mostly expressed in HNSCC tissues with ~ 125 transcripts per million (TPM) after the ovarian (OV, ~198 TPM) and lung adenocarcinoma (LUAD, ~195 TPM)." (PMID 31861233, 2019).
sarcoma (18 papers, 2012 to 2024). A usually aggressive malignant neoplasm of the soft tissue or bone. "Their result showed that tumor-associated macrophages (TAMs) in sarcomas are triggered by CD47 monoclonal antibodies (mAbs) and can kill cancer cells." (PMID 33672770, 2021). "CD47 monoclonal antibodies (mAbs) activate tumor-associated macrophages (TAMs) in sarcomas to phagocytose and eliminate cancer cells." (PMID 30674867, 2019). "The only existing study showed bimodal expression of CD47, where most of the tissue microarrays of sarcoma had either 0% or > 90% positivity in tumor cells." (PMID 38493445, 2024). "Despite active preclinical and clinical evaluations of recently developed CD47 antibodies, especially in hematological malignancies, data on sarcomas remain limited." (PMID 39594611, 2024). "First, we have analyzed CD47 abundance in all sarcoma samples (n = 55) to evaluate its presence in general." (PMID 38493445, 2024). "Treatment with monoclonal antibodies against CD47 resulted in sarcoma cell phagocytosis by TAM and significant tumor growth reduction in mouse models." (PMID 31376208, 2019). "Recent work in animal models has demonstrated that anticancer activity from TAM can be activated in sarcomas by blocking CD47." (PMID 31376208, 2019). "Macrophages are the predominant immune cell population infiltrating sarcoma tissues, and the evasion of immune surveillance through CD47 signaling may facilitate metastasis." (PMID 39594611, 2024). "Thus, we now investigate phagocytosis of pediatric sarcoma cells after XVir- and combination therapy with CD47 inhibition (CD47i) in more detail." (PMID 38357194, 2024). "Our results suggest that while CD47 expression is prevalent in various sarcoma subtypes, its impact on survival outcomes and prognostic relevance may be limited." (PMID 38493445, 2024). "Therefore, inhibition of CD47-SIRPα-complex should be tested in sarcoma patients, as this treatment strategy has shown promising results in other cancers." (PMID 36900335, 2023). "Clinical trials with anti-CD47 in patients with sarcomas are ongoing." (PMID 33717062, 2021). "As the histiocytic (myeloid) sarcomas studied here included a majority population of CD47+ tumor cells, the detection and targeting of CD47 in these tumors may present a useful therapeutic target." (PMID 22952867, 2012). "Significant positive correlations between CD47 and IFT57 mRNA expression extended to neuroendocrine tumors, sarcomas, and some hematologic malignancies, but IFT57 and CD47 co-expression had lower Spearman’s coefficients and rank orders in these cancers." (PMID 39201643, 2024). "This study highlights the potential of the CD47 molecule as a promising immunotherapeutic target in STS, particularly given its elevated expression levels in diverse sarcoma types." (PMID 38493445, 2024). "In all of these sarcomas, the expression of the SIRPA receptor was poorly correlated with the expression of CD47 in tumors." (PMID 37958467, 2023). "Our new prognostic profile could allow clinicians to select sarcoma patients for adjuvant treatment or a more aggressive treatment strategy, and the presence of serum macrophage markers could serve as serum biomarkers for CD47 inhibitor immunotherapy in sarcoma." (PMID 36900335, 2023). "Delivering a “don’t eat me” signal, expression of CD47 on tumor cells was demonstrated to be among the highest in DDLPS and PLPS compared to other sarcoma subtypes." (PMID 36230502, 2022). "CD47, SIRPα, and TIM3 are all expressed on TAMs, and chordoma CD47 expression shows the highest degree of expression among various sarcomas, However, whether it can be used as a prognostic factor and therapeutic target for chordoma is currently unknown." (PMID 37720221, 2023).
sarcoma (continued). "Furthermore, the expression of CD47 and SIRPA showed poor positive correlations with CD68+ and CD163+ macrophages in almost all sarcomas, except a solitary fibrous tumor, demonstrating a significant negative correlation between CD163+ and CD68+ TAMs, and CD47." (PMID 37958467, 2023). "However, CD47 mAb monotherapy could not cure sarcoma‐bearing mice." (PMID 31376208, 2019).
autoimmune disease (17 papers, 2013 to 2025). A disorder resulting from loss of function or tissue destruction of an organ or multiple organs, arising from humoral or cellular immune responses of the individual to their own tissue constituents. "While CD47 was expressed in normal DCs (mDCs and pDCs subsets) associated with immune evasion and anti-phagocytic properties, in autoimmune diseases and inflammatory-related diseases, CD47 is highly expressed in monocytes." (PMID 38742110, 2024). "Studies using mouse models of autoimmune diseases have found that CD47-SIRPα and CD24-SIGLEC10 polymorphisms affect macrophages’ phagocytosis of apoptotic cells, suggesting that modulating the CD24-SIGLEC10 axis may have potential value in various musculoskeletal disorders." (PMID 37545490, 2023). "Allogeneic, immune-evasive hypoimmune (HIP) cell therapeutics that are HLA-depleted and overexpress CD47 create the opportunity to treat immunocompetent patients with cancer, degenerative, or autoimmune diseases." (PMID 40251154, 2025). "Prospects of CD47 boosting and blocking are considered along with potential therapeutic implications for autoimmune diseases and cancer." (PMID 38362603, 2024). "Recently, the involvement of CD47 in autoimmune diseases, including systemic lupus erythematosus (SLE), has been described." (PMID 37368493, 2023). "CD47/signal-regulatory protein alpha (SIRPα) is closely related to developing autoimmune diseases by promoting inflammatory response." (PMID 38111586, 2023). "The SIRPα - CD47 axis plays an important role in immune cell homeostasis and in leukocyte trafficking in inflammatory and autoimmune disease models." (PMID 35413056, 2022). "Studies have shown that CD47 not only takes part in autoimmune diseases and tumors but also plays a key role in IRI-related diseases in kidneys and hearts." (PMID 34239692, 2021). "An autoimmune disease model in the brain recently reported the similar findings that CD47-/- CD4+ T cells were activated and produced even larger amounts of cytokines compared to WT mice." (PMID 34093583, 2021). "The functions of CD47 on autoreactive B cells and how interacting T cells drive autoimmune diseases such as systemic lupus erythematous and rheumatoid arthritis merit further study, including investigation of the function of CD47 on EVs released by these activated immune cells." (PMID 40943300, 2025). "This is followed by thoughts on what might be done, known as plan B, to identify advantages within the CD47 ECD for modulating tolerance in autoimmune diseases." (PMID 41511354, 2025). "This review helps to understand the biology of CD47, and provides valuable new information that may help develop effective CD47-targeting therapies for the treatment of cancers, autoimmune diseases, and transplant rejection." (PMID 38426113, 2024). "Thus, it is important to understand the mechanism of immune response under the blockade of CD47, particularly in autoimmune diseases." (PMID 37368493, 2023). "CD47-SIRP α signaling pathway is related to the development of autoimmune diseases." (PMID 38111586, 2023). "The therapeutic effect may be influenced by the timing of CD47 inhibition in the development of autoimmune diseases." (PMID 37368493, 2023). "Several reports suggest that CD47 is crucial in the development of certain autoimmune diseases." (PMID 34068752, 2021). "In the future, more studies and clinical trials may focus on the application of CD47-SIRPα and CD24-SIGLEC10 axes in autoimmune diseases." (PMID 37545490, 2023). "Thus, this CD47-SIRPα interaction between DCs and CD4+ T cells has the potential to be an important mechanism in the pathogenesis of autoimmune diseases." (PMID 34093583, 2021).
head and neck squamous cell carcinoma (16 papers, 2016 to 2026). A squamous cell carcinoma that arises from any of the following anatomic sites: lip and oral cavity, nasal cavity, paranasal sinuses, pharynx, larynx, and salivary glands. "For instance, a study of head-and-neck squamous cell carcinoma demonstrated that raised CD47 expression is associated with decreased natural NK cell-mediated cytotoxicity, while anti-CD47 antibody treatment enhanced NK cell-mediated cytotoxicity." (PMID 32082311, 2020). "In parallel, the role of the SIRPα/CD47 axis has been described in head and neck squamous cell carcinoma (HNSCC)." (PMID 36829496, 2023). "Moreover, anti-CD47 treatment reinvigorate effector T cells in head and neck squamous cell carcinoma mouse model and alters tumor microenvironment via reducing the infiltration of Tregs and myeloid-derived suppressor cells (MDSCs) and decrease the suppressive function of MDSCs." (PMID 40070841, 2025). "Head and neck squamous cell carcinoma (HNSCC) cells with a high level of expression of CD47 show lower NK cytotoxicity, which is reversed upon anti-CD47 treatment." (PMID 35164813, 2022). "Head and neck squamous cell carcinoma also showed significant correlations between IFT57 mRNA expression higher than the mean and decreased overall survival that was not significant for CD47." (PMID 39201643, 2024).